ARMC5 (armadillo repeat containing 5)
Diseases named in the same sentence as ARMC5 in open-access papers (continued):
Sharing a sentence is not in itself a finding about the gene and the disease.
primary aldosteronism (7 papers, 2018 to 2026). An endocrine disorder characterized by excessive production of aldosterone by the adrenal glands. "Among them, variants in the ARMC5 gene appear to be a rare but inherited cause of primary aldosteronism and consequently low-renin hypertension in African Americans." (PMID 30832344, 2019). "Our laboratory has recently identified an association between biallelic variants of ARMC5 in African Americans and primary aldosteronism." (PMID 30832344, 2019). "Besides, the systematic ARMC5 germline screening in 56 patients with primary aldosteronism identified possibly deleterious variants in 6 unrelated African-American patients." (PMID 39910635, 2025). "The complexity of this case, with coexisting obesity and the ARMC5 variant, makes it challenging to definitively rule out a mild form of primary aldosteronism." (PMID 40130155, 2025). "Additionally, no ARMC5 variant has been found in an independent series of patients with primary aldosteronism and bilateral adrenal hyperplasia, nor in a series of 4 families with familial hyperaldosteronism type II." (PMID 39910635, 2025).
Hypertension (6 papers, 2019 to 2026). The presence of chronic increased pressure in the systemic arterial system. "Specifically, the average age at diagnosis was lower in ARMC5 variant group than in wild-type ARMC5 group, while the prevalence of clinical CS and hypertension as well as the weight and number of adrenal nodules were higher." (PMID 35996143, 2022). "All patients carrying a damaging ARMC5 variant were African Americans suggesting that ARMC5 pathogenic variants might contribute to the known increased predisposition of this population to low renin hypertension." (PMID 36004349, 2022). "We hypothesized that a direct association between ARMC5 variants and increased risk of hypertension in African American exists." (PMID 30832344, 2019).
adenoma (4 papers, 2020 to 2025). A neoplasm arising from the epithelium. "Conversely, no concomitant CTNNB1, PRKACA, PRKAR1A or GNAS somatic variant (classically met in cortisol-producing adenomas) with a germline ARMC5 alteration has been yet reported to our knowledge." (PMID 39910635, 2025). "However, we cannot imply that the cases without ARMC5 germline mutations could be adenoma or PMAH not related to ARMC5." (PMID 32117062, 2020).
adrenal incidentaloma (4 papers, 2018 to 2025). "Perhaps the unilateral adrenal mass of F1-II-4 is just a typical adrenal adenoma with a different pathogenic mechanism from the bilateral adrenal masses of her siblings who carried ARMC5 pathogenic germline mutations." (PMID 29370219, 2018). "In conclusion, according to our results, the absence of pathogenic allelic variants in ARMC5 from patients with unilateral adrenal incidentalomas points out that other mechanisms may justify this common finding in clinical practice." (PMID 32117062, 2020). "It is not clear if apparently sporadic cases of PMAH diagnosed as unilateral or bilateral adrenal incidentalomas, where familial clinical screening has not been performed, should be screened to ARMC5 analysis." (PMID 32117062, 2020).
adrenocortical cancer (4 papers, 2018 to 2025). "In vitro experiments show ARMC5 missense variants identified in human adrenocortical cancer cell line (H295R), leads to loss of apoptosis activity, suggesting that these variants affect ARMC5’s pro‐apoptotic function." (PMID 33544460, 2021). "Macronodular adrenal hyperplasia was linked to ARMC5 defects and new genes were found to be involved in adrenocortical cancer (ACC)." (PMID 30456751, 2018). "Indeed, on one hand, the pro-apoptotic effect of wild-type ARMC5 transfected in adrenocortical carcinoma cell line H295R is lost when the cells are transfected with the ARMC5 mutants, likely to explain the adrenal tumorigenesis." (PMID 39910635, 2025). "Recently, a group reported the results of a systematic germline genetic screening of patients with adrenocortical carcinoma (ACC), including ARMC5 sequencing." (PMID 39910635, 2025).
hyperplasia (3 papers, 2018 to 2022). An abnormal increase in the number of cells in an organ or a tissue with consequent enlargement. "In addition, the development of adrenal hyperplasia with increasing age in Armc5 knock out mice illustrates the key role of Armc5 in the adrenal." (PMID 36004349, 2022).
primary macronodular adrenal hyperplasia (3 papers, 2020 to 2022). "The mutation of ARMC5 gene was frequently detected in primary macronodular adrenal hyperplasia, but there has been no research detecting mutation status of ARMC5 in ACC tissues." (PMID 33564960, 2021).
adrenal tumor (2 papers, 2025). "Previous reports have documented the co-occurrence of extra-adrenal tumors, such as breast cancer, parathyroid tumors, thyroid cancer, and thyroid adenomas, in individuals with ARMC5 variants." (PMID 40895499, 2025).
dyslipidemia (2 papers, 2022 to 2024). "Since E3 ligases are potential targets for small molecules, ARMC5 might be a candidate for the treatment of metabolic syndrome." (PMID 35862218, 2022). "ARMC5 may become a novel therapeutic target in the treatment of SREBF-related diseases, such as hepatosteatosis, dyslipidemia, atherosclerosis, and tumorigenesis." (PMID 39491648, 2024). "As ARMC5 was ubiquitously expressed, and SREBF plays important roles in metabolism, including diabetes, dyslipidemia, and liver steatosis, ARMC5 might also be an important factor beyond BMAH." (PMID 35862218, 2022).
intracranial meningioma (2 papers, 2022 to 2026). A meningioma that arises within the cranial cavity. "Beyond PBMAH, ARMC5 mutations have been associated with other neoplasms, including intracranial meningiomas." (PMID 41503047, 2026). "Regarding germline mutations in ARMC5, it has been suggested that it could play a pathogenic role in the development of other tumors such as intracranial meningiomas." (PMID 35992106, 2022).
Obesity (2 papers, 2024 to 2025). Accumulation of substantial excess body fat. "We suggest that the synergistic effect of obesity promotion and increased mineralocorticoid activity, based on the ARMC5 loss-of-function mutation, caused hypokalemia in this case." (PMID 40130155, 2025). "This case report describes an instance of unexplained hypokalemia and obesity in a patient with a heterozygous ARMC5 variant." (PMID 40130155, 2025). "Although these findings suggest potential connections between ARMC5 variants, obesity, and endocrine regulation, the exact mechanisms remain poorly understood." (PMID 40130155, 2025). "In conclusion, this case highlights the potential connection between an ARMC5 variant and unexplained hypokalemia in a patient with obesity." (PMID 40130155, 2025). "This case describes an association between an ARMC5 variant, unexplained hypokalemia, and obesity." (PMID 40130155, 2025). "Next, to explore the role of adipocyte Armc5 in obesity, we fed AdArmc5 KO with a high fat-high sucrose diet (HF/HSD) from 4-week-old." (PMID 39491648, 2024). "As the patient also presented with obesity, and given that previous mouse and in vitro studies suggest possible interactions between ARMC5 and mineralocorticoid pathways, we hypothesize that the mechanism of hypokalemia may involve adipose tissue function." (PMID 40130155, 2025).
Primary hyperaldosteronism (2 papers, 2022 to 2026). A form of hyperaldosteronism caused by a defect within the adrenal gland. "Other endocrine comorbidities, such as primary hyperaldosteronism, hyperparathyroidism, and multinodular goiter, have also been described in carriers of ARMC5 pathogenic variants." (PMID 41503047, 2026).
renal carcinoma (2 papers, 2021 to 2023). A carcinoma arising from the epithelium of the renal parenchyma or the renal pelvis. "USP7 altered cell cycle G1/S phases and regulated renal cancer cell proliferation by targeting ARMC5." (PMID 37259026, 2023). "In the study, we demonstrated that ARMC5 was decreased at protein levels in the renal cancer cell tissues and lines." (PMID 33544460, 2021). "A Western blot analysis of ARMC5 was performed and showed that the expression of ARMC5 was decreased in the renal cancer cell tissues and lines." (PMID 33544460, 2021). "In the present study, we found that the expression of ARMC5 was decreased at protein levels in the renal cancer cell tissues and lines." (PMID 33544460, 2021). "Moreover, USP7 altered cell cycle G1/S phases and regulated renal cancer cell proliferation by targeting ARMC5." (PMID 33544460, 2021).
viral disease (2 papers, 2022). "Studies in rat models suggested a possible link between ARMC5 damaging variants and the impairment of the cell-mediated immune response, leading to a higher susceptibility to bacterial and viral infections." (PMID 35368666, 2022).
adrenocortical tumor (1 paper, 2022). "Although ARMC5 inhibits adrenocortical tumor growth and is considered a tumor-suppressor gene, its molecular function is poorly understood." (PMID 35862218, 2022).
Carney complex (1 paper, 2025). Carney complex (CNC) is characterized by spotty skin pigmentation, endocrine overactivity and myxomas. "PBMAH is associated with ARMC5 mutations, whereas PPNAD is linked to Carney complex and involves PRKAR1A mutations." (PMID 41000299, 2025).
celiac disease (1 paper, 2020). An autoimmune genetic disorder with an unknown pattern of inheritance that primarily affects the digestive tract. "In a single patient with a diagnosis of celiac disease who underwent abdominal CT imaging and was diagnosed with bilateral adrenal nodules, we identified the ARMC5 pathogenic allelic variant c.1084C > T p.Arg362Trp, which is located on exon 3 of ARMC5 (35*)." (PMID 32117062, 2020).
colonic adenomas (1 paper, 2025). "Here, we report 2 siblings with PBMAH and colonic adenomas harboring a novel germline pathogenic variant (c.2647del) of the ARMC5 gene." (PMID 40895499, 2025).
colorectal adenoma (1 paper, 2025). An adenoma that arises from the colon or rectum. "Notably, both patients developed colorectal adenomas, suggesting a potential link between ARMC5 germline pathogenic variants and colorectal adenoma development." (PMID 40895499, 2025). "Colorectal adenomas might be associated with ARMC5 gene pathogenic variants in PBMAH." (PMID 40895499, 2025). "The genetic analysis of colorectal adenomas in both siblings revealed a germline pathogenic variant in the ARMC5 gene, without evidence of additional somatic variants." (PMID 40895499, 2025). "A link between ARMC5 variants and the development of colorectal adenomas has not been reported." (PMID 40895499, 2025).
colorectal tumors (1 paper, 2025). "Our experience suggests that ARMC5 gene pathogenic variants are associated with colorectal tumors as well as PBMAH." (PMID 40895499, 2025).
electrolyte disorders (1 paper, 2025). "Understanding the prevalence of electrolyte disorders in patients with ARMC5 variants could help establish whether this association occurs more broadly." (PMID 40130155, 2025).
exophthalmos (1 paper, 2018). "We demonstrated extensive genetic diversity of ARMC5 in a patient with PBMAH that started with exophthalmos, which further expands the molecular pathophysiology of this disease." (PMID 29343284, 2018).
experimental autoimmune encephalomyelitis (1 paper, 2017). An autoimmune demyelinating disease of the central nervous system that is produced experimentally in animals by the injection of homogenized brain or spinal cord in Freund's adjuvant. "To understand the role of ARMC5 in in vivo T-cell immune responses, particularly CD4-mediated immune responses, we induced experimental autoimmune encephalomyelitis (EAE) in Armc5 WT and KO mice." (PMID 28169274, 2017).
myelomeningocele (1 paper, 2024). Myelomeningocele is the most severe form of spina bifida. "A human genetic study discovered nine highly deleterious single-nucleotide variants (SNVs) in the ARMC5 exons of myelomeningocele (MM) patients; four of the nine SNVs were proven essential for the POLR2A-specific E3 activity." (PMID 38225631, 2024). "We also identify nine deleterious mutations in the ARMC5 gene in 511 patients with myelomeningocele, a severe form of spina bifida." (PMID 38225631, 2024).
neuroendocrine tumors (1 paper, 2022). "Similarly, ARMC5 (OMIM: 615549; 16p11.2) variants have also been found to cause sporadic neuroendocrine tumors and multiple endocrine neoplasia type-1 (MEN1; OMIM: 131100)." (PMID 36553564, 2022).
pituitary adenoma (1 paper, 2026). "This is the second case report of a patient with both PBMAH and a pituitary adenoma, presenting with a germline ARMC5 variant." (PMID 41503047, 2026).
pituitary tumor (1 paper, 2026). A benign or malignant neoplasm affecting the pituitary gland. "In conclusion, this case contributes to the expanding phenotype of ARMC5-associated disease and raises questions about its role in the pathogenesis of pituitary tumors." (PMID 41503047, 2026).
renal cell carcinoma (1 paper, 2023). "For example, USP7 delayed renal cell carcinoma progression via deubiquitylating and stabilizing ARMC5." (PMID 38129408, 2023).
spina bifida (1 paper, 2024). A congenital neural tube defect in which vertebrae are not fully formed. "We find that ARMC5 knockout mice have increased incidence of NTDs, such as spina bifida and exencephaly." (PMID 38225631, 2024).
tumor (20 papers, 2014 to 2026). "The pathogenicity of ARMC5 variants is established on the basis of their frequency in the general population, in silico predictions, familial segregation and tumor DNA sequencing." (PMID 39910635, 2025). "ARMC5 mutations are due to a biallelic inactivation that is compatible to a tumour suppressor gene model (germline and subsequent somatic mutation)." (PMID 37796369, 2024). "The inactivation of the ARMC5 gene, a potential tumor suppressor gene, is one of the associated causes of PMAH." (PMID 36553033, 2022). "Using WES (whole-exome sequencing) of the germline and tumor DNA, we first identified a novel heterozygous germline ARMC5 mutation (c." (PMID 29587644, 2018). "ARMC5 somatic mutations have been detected in hyperplastic adrenocortical nodules of PBMAH patients in addition to the germline mutations, supporting a ‘two-hit’ model for ARMC5 as a tumor suppressor gene." (PMID 29370219, 2018). "Patients with ARMC5 mutations present with larger tumor volumes, increased numbers of tumor nodules, and more severe hypercortisolism." (PMID 26106367, 2015). "Loss of ARMC5 function may contribute to tumor formation through a 2-hit mechanism—a germline mutation followed by a somatic event that affects the second allele." (PMID 41503047, 2026). "In patients with a germline heterozygous mutation of a given tumor suppressor gene (inherited or de novo), the occurrence of a somatic mutation on the other allele of the same gene in a unique cell (an adrenocortical cell in the case of ARMC5) leads to the loss of both alleles." (PMID 39910635, 2025). "Taking into account the tumor suppressor gene model of ARMC5, extra-adrenal tumoral DNA has been analyzed for bi-allelic ARMC5 alterations." (PMID 39910635, 2025). "All tumor samples of those 18 patients carried two genetic alterations in the ARMC5 locus; however, their leukocyte DNA only carried one of the two suggesting that ARMC5 is a tumor suppressor gene." (PMID 35625779, 2022). "Genotyping of blood and tumor DNA from 33 patients with PBMAH, identified ARMC5 (16p11.2 locus) variants in 18 of them (55%)." (PMID 35625779, 2022). "To assess expression levels of ARMC5 in RCC, we first measured protein levels of ARMC5 in paired non‐tumour tissue and RCC obtained from the Pathology Department." (PMID 33544460, 2021). "Whole genome sequencing of 5 paired tumor and leucocyte DNA samples identified ARMC5 gene alterations, mapping to 16p11.2, as responsible for PBMAH." (PMID 32783015, 2020). "A first inactivating alteration was observed in the patients’ leukocyte DNA and a second event in somatic DNA extracted from adrenal nodules, suggesting a tumor suppressor role of the ARMC5 gene." (PMID 32783015, 2020). "Investigation into the genetic origin of AIMAH led to the genotyping (both blood and tumor) of 33 patients with AIMAH, with detection of inactivating ARMC5 gene mutations in 55% (18/33) of tumors." (PMID 30456751, 2018). "Inactivation of ARMC5 in BMAH follows the “two-hit” model of a tumor suppressor gene responsible for a hereditary neoplasia syndrome." (PMID 29587644, 2018). "In many familial cases of BMAH, mutations in armadillo repeat containing 5 (ARMC5), a putative tumor suppressor gene, are thought to induce the disorder." (PMID 29587644, 2018). "ARMC5 is a tumor suppressor gene that encodes a cytosolic protein with no enzymatic activity that has an armadillo repeat domain, similar to the gene for β-catenin." (PMID 35625779, 2022). "SREBF was involved in the tumor-suppressor function of ARMC5 in adrenocortical cells." (PMID 35862218, 2022). "This suggests the role of ARMC5 as being a tumor-suppressor gene, with tumor development as described in Knudson’s two-hit hypothesis, when a secondary somatic inactivating mutation occurs in one allele in the setting of a preexisting germline inactivating mutation in the alternate allele." (PMID 30456751, 2018).
cancer (1 paper, 2022). A tumor composed of atypical neoplastic, often pleomorphic cells that invade other tissues. "Furthermore, the diagnosis of an inherited germline mutation in cancer predisposition genes, such as ARMC5, can be applied in preimplantation genetic diagnosis (PGD) to prevent the occurrence of cancerous patients." (PMID 36553033, 2022).
genetic disease (1 paper, 2022). "As a genetic disease, PBMAH is reported to be associated with germline mutation in ARMC5 gene." (PMID 36561559, 2022).
nervous system disorder (1 paper, 2022). A non-neoplastic or neoplastic disorder that affects the brain, spinal cord, or peripheral nerves. "On the other hand, the ARMC proteins including ARMC4, ARMC5, ARMC6, ARMC7, ARMC8, ARMC10, and ARMCX3 regulate the Wnt signaling pathway leading to specific nervous system disorders." (PMID 36553564, 2022).
ARMC5 also shares sentences with these, for which no sentence is quoted: atherosclerosis (1 paper); breast carcinoma (1); diabetes (1); endocrine disorders (1); glioma (1); hyperandrogenism (1); hyperparathyroidism (1); Hypokalemia (1); infection (1); multinodular goiter (1); Myelolipoma (1); pancreatic NET (1); parathyroid tumors (1); peripheral T cell lymphoma (1); pheochromocytoma (1); pigmented nodular adrenocortical disease (1); Thyroid adenoma (1); thyroid cancer (1); thyroid tumor (1).